PHOSPHO1 (phosphoethanolamine/phosphocholine phosphatase 1)
Description:
Phosphatase that has a high activity toward phosphoethanolamine (PEA) and phosphocholine (PCho). Involved in the generation of inorganic phosphate for bone mineralization (By similarity). Acts in a non-redundant manner with PHOSPHO1 in skeletal mineralization: while PHOSPHO1 mediates the initiation of hydroxyapatite crystallization in the matrix vesicles (MVs), ALPL/TNAP catalyzes the spread of hydroxyapatite crystallization in the extracellular matrix (By similarity).
Tractability: Small molecule: a high-quality ligand is known; it belongs to a druggable protein family. Antibody: its Gene Ontology location is reachable by antibodies, with medium confidence; the Human Protein Atlas places it where antibodies can reach. PROTAC: a small molecule that binds it is known.
Target class: Enzyme; Phosphatase
Chemical probes: ML086
Gene: Protein-coding gene on chromosome 17 (49,223,366 to 49,230,787, reverse strand). Ensembl gene ENSG00000173868.
Subcellular location: Extracellular vesicle
Subcellular location (Human Protein Atlas): Actin filaments; Plasma membrane
Pathways (Reactome):
Metabolism: Synthesis of PC; Synthesis of PE
Gene Ontology:
Molecular function: phosphocholine phosphatase activity; phosphoethanolamine phosphatase activity; protein binding; pyrophosphatase activity; phosphatase activity
Biological process: bone mineralization; bone mineralization involved in bone maturation
Cellular component: cytosol; extracellular membrane-bounded organelle; extracellular vesicle; extracellular matrix
Genetic constraint (gnomAD): Loss-of-function variants: 6 observed, 9 expected, observed/expected ratio (o/e) 0.67, 90% interval 0.36 to 1.31. That is too few expected variants to judge how well the gene tolerates losing a copy. Missense variants: 330 observed, 306.96 expected, observed/expected ratio (o/e) 1.08, 90% interval 0.98 to 1.18. Synonymous variants: 159 observed, 132.95 expected, observed/expected ratio (o/e) 1.2, 90% interval 1.05 to 1.36.
Homologues: Orthologues: chimpanzee PHOSPHO1 (99% identical), dog PHOSPHO1 (96% identical), rabbit PHOSPHO1 (96% identical), mouse Phospho1 (93% identical), macaque PHOSPHO1 (91% identical), rat Phospho1 (90% identical), guinea pig PHOSPHO1 (72% identical), tropical clawed frog phospho1 (51% identical), zebrafish phospho1 (49% identical), Drosophila melanogaster CG12237 (30% identical), Drosophila melanogaster CG14212 (25% identical). Paralogues in human: PHOSPHO2 (37% identical).